TLR4 (toll like receptor 4)
Diseases named in the same sentence as TLR4 in open-access papers (continued):
Sharing a sentence is not in itself a finding about the gene and the disease.
Miscarriage (5 papers, 2018 to 2024). A pregnancy that ends at a stage in which the fetus is incapable of surviving on its own, defined as the spontaneous loss of a fetus before the 22th week of pregnancy. "TLR9 AA, IL-10 AA, and TLR4 CC interaction (z = 44.826, p < 0.001) and TLR9 GG, IL-10 CA, and TLR4 CT interaction (z = 44.826, p < 0.001) had a statistically significant positive effect on the risk of miscarriage." (PMID 30116270, 2018). "LPS/TLR4 signaling is associated with miscarriage, and is used to induce models of abortion." (PMID 37226177, 2023). "In contrast, increases in TLR4 expression on maternal monocytes, which may be responding to fibrinogen, are correlated with spontaneous preterm labor, and increased expression in maternal decidua has been linked to recurrent miscarriages." (PMID 31178840, 2019). "The association of TLR4 was studied in women with aPL (antiphospholipid antibodies), which activate the TLR4 pathway and the inflammatory response in trophoblasts leading to miscarriages, PE, and PTB." (PMID 32508811, 2020). "TLR2, TLR4, IL-6, IL-8, and PGR SNPs can also affect the risk of miscarriage, but in less extent than TLR9 and IL-10." (PMID 30116270, 2018). "The multiple logistic regression analysis has also shown that the following double interactions showed statistically significant association with the risk of miscarriage: TLR9 and IL-10; TLR9 and IL-8; TLR9 and IL-6; and IL-10 and TLR4." (PMID 30116270, 2018). "The following triple genetic interaction showed statistically significant association with the risk of miscarriage: TLR9, IL-10, and TLR4." (PMID 30116270, 2018). "The following double genetic interactions showed statistically significant association with the risk of miscarriage: TLR9 and IL-6; TLR9 and IL-8; TLR9 and IL-10; and IL-10 and TLR4." (PMID 30116270, 2018). "TLR2, TLR4, IL-6, IL-8, and PGR SNPs were identified as secondary factors that can also affect the risk of miscarriage." (PMID 30116270, 2018). "Moreover, one triple genetic interaction was significantly associated with the risk of miscarriage: TLR9, IL-10, and TLR4." (PMID 30116270, 2018). "Additionally, the impact of herpes simplex viruses 1 and 2 on the expression of TLR2, TLR3, TLR4 and TLR8 in predicting miscarriage onset has been studied." (PMID 39273663, 2024).
multiple system atrophy (5 papers, 2015 to 2024). Multiple system atrophy (MSA) is a neurodegenerative disorder characterized by autonomic failure (cardiovascular and/or urinary), parkinsonism, cerebellar impairment and corticospinal signs with a median survival of 6-9 years. "Upregulation of TLR4 has been detected in multiple system atrophy, both in the brains of patients with the disease and in brains from a transgenic mouse model of the disease." (PMID 26346361, 2015). "Regarding PRRs, such as TLR4 and TLR2, have been demonstrated that are able to bind to α-synuclein in multiple system atrophy (MSA) models, where the overexpression of α-synuclein increases motor impairment as well as dopaminergic degeneration in the SNpc." (PMID 30618635, 2018).
myositis (5 papers, 2013 to 2023). "Regarding the specific and associated myositis antibodies, the monocytes from patients with anti Mi2 antibodies had a higher expression of TLR4+." (PMID 32164729, 2020). "In addition, immunomodulators such as fibrinogen and HMGB1 are correlated with the progression of myositis and are believed to induce autophagy by signaling through TLR-4, indicating a probable association with innate immune mechanisms." (PMID 23758833, 2013). "The murine models of myositis have demonstrated the importance of TLR2 and TLR4 in the induction of disease in IIM, since the deficiency of both TLRs or their signaling protein MyD88 completely abolish the disease phenotype." (PMID 32164729, 2020). "The pro-inflammatory effect of HMGB1 in myositis was mainly mediated by TLR4." (PMID 35250993, 2022). "Extracellular HMGB1 also promoted muscle fatigue through TLR4 in patients and mice with myositis." (PMID 35250993, 2022). "The interaction of HMGB1 with toll-like receptor 4 (TLR4) induces muscle weakness and fatigue in patients with myositis, while the binding of HMGB1 to the receptor for advanced glycation end-products (RAGE) decreases survival in muscle-wasting mouse models." (PMID 36497194, 2022). "A recent study reported that HMGB1 induced muscle fatigue occurs via the TLR-4 pathway in muscle and that the HMGB1-TLR-4 pathway plays a role in the pathogenesis of myositis patients." (PMID 23758833, 2013). "Although antigen-specific T cell proliferation and production of class-switched autoantibodies suggest a role for adaptive immunity in this model, the development of myositis is absolutely dependent on MyD88, with substantial (but overlapping) contributions from TLR2 and TLR4 signaling." (PMID 37809058, 2023). "In fact, muscle biopsies of myositis patients show a significantly increased expression of TLR-2, TLR-3, TLR-4, and TLR-9 in the skeletal muscle and infiltrating cells as well as the enhanced expression of cytokines such as IFN-γ, IL-4, IL-17, TNF-α, IL-6 and type 1 IFNs." (PMID 23758833, 2013).
ovarian tumor (5 papers, 2012 to 2025). "Collectively, the TLR4+/MyD88- phenotype was associated with all types of tissue, including non-dysplastic epithelium, while TLR4+/MyD88+ (co-expression) was associated only with ovarian neoplasms." (PMID 24977712, 2014). "Escherichia coli lipopolysaccharides trigger inflammatory responses in ovarian tumor cells, promoting growth and chemoresistance via the inflammatory TLR-4-MyD88 pathway." (PMID 41148804, 2025). "ELISAs were employed to measure cytokine release from breast and ovarian tumor cells in response to several structurally distinct chemotherapy agents and/or TLR4 agonists or antagonists." (PMID 28915246, 2017). "In ovarian tumors, functional activity for TLR4 was demonstrated by stimulation of cell lines with specific ligands and subsequent activation and translocation of NF-κB and release of the proinflammatory cytokines interleukin-6 and CCL-2." (PMID 22985132, 2012). "The aim of this study was to comprehensively characterise the distribution and clinical significance of TLR4 and MyD88 expression in a cohort of ovarian neoplasms, which includes all common histologic subtypes and represents the largest such series studied to date." (PMID 24977712, 2014). "To identify potential regulators of TLR4 signaling in microglia, we overexpressed FLAG‐tagged DUBs of the ovarian tumor protease (OTU) family in BV2 cells and then stimulated them with LPS for 6 hours." (PMID 40755418, 2025).
papillary thyroid cancer (5 papers, 2013 to 2023). "Exosomal circ_0006156 enhanced cell survival in papillary thyroid cancer (PTC) via miR-1178/TLR4 pathway to modulate PTC progression." (PMID 35333693, 2022). "For example, circ_0006156 had higher expression in serum exosomes, and through the miR-1178/TLR4 axis, it could accelerate papillary thyroid cancer to bad prognosis." (PMID 34153004, 2021).
pneumococcal pneumonia (5 papers, 2007 to 2019). A febrile disease caused by STREPTOCOCCUS PNEUMONIAE. "Our laboratory recently demonstrated that TLR2 and TLR4 interact in the recognition of S. pneumoniae and that pneumolysin-induced TLR4 signalling can compensate for TLR2 deficiency during pneumococcal pneumonia." (PMID 22721450, 2012). "Among these, TLR2 and TLR4 are thought to be critical in bacterial infections and have been studied in pneumococcal pneumonia." (PMID 29922273, 2018). "In contrast, TLR4 was only protective against a low inoculum in another model of pneumococcal pneumonia." (PMID 17257395, 2007). "The amelioration of inflammatory responses in the lung during pneumococcal pneumonia by ibrutinib may also result from inhibition of other Btk-dependent receptors that regulated S. pneumoniae-induced lung inflammation, including TLR4, TLR9, TREM-1 and NLRP3." (PMID 30646846, 2019). "Furthermore, Ply has been shown to interact with TLR-4 and to induce TLR-4 independent activation of the NLRP3 inflammasome, contributing to host protection against pneumococcal pneumonia and lethal infection." (PMID 23533636, 2013).
pregnancy disorder (5 papers, 2013 to 2021). A disorder that is related to pregnancy. "It remains to be determined whether impaired TLR4 signaling, perhaps as a consequence of altered seminal fluid composition in men, or dysregulated TLR4 expression or TLR4 gene polymorphisms in women, contributes to fertility or pregnancy disorders in the clinical setting." (PMID 34400677, 2021). "So far, previous research showed the participation of several single-nucleotide polymorphisms (SNPs) of TLR2, TLR4, and TLR9 in various diseases and pregnancy disorders." (PMID 23161283, 2013). "List of drugs targeting TLR4, and its downstream signaling molecules during pregnancy disorder." (PMID 32508811, 2020). "However, previous studies commonly showed the role of TLR4 896 A>G and 1196 C>T SNPs in several pregnancy disorders, including premature rupture of membranes (PROM), bronchopulmonary dysplasia, and preterm labor." (PMID 26254559, 2015). "Further studies are undergoing to confirm the relevance of the MyD88-dependent LPS/Tlr4 pathway in inducing LPS-induced defects at the EBIS such that therapies targeted at blocking LPS signaling for the management of infection-induced early pregnancy disorders can be found." (PMID 34360700, 2021). "Hence, increased levels of TLR4 on leucocytes or cells of maternal and fetal origin could be used as a biomarker for pregnancy disorders." (PMID 32508811, 2020). "In most pregnancy disorders, such as PTB, PE, or placental malaria, the TLR4 expression is upregulated in immune cells or in maternal derived cells, leading to the aberrant production of pro-inflammatory cytokines at the materno–fetal interface." (PMID 32508811, 2020). "One possible modification influencing gene function, which was also confirmed in case of TLR2, TLR4, and TLR9 genes in accordance to different diseases and pregnancy disorders, is the occurrence of SNPs within the genetic sequence." (PMID 23161283, 2013). "To date, there has been a lack of knowledge regarding whether TLR4 accessories such as CD14 and MD-2 are important in pregnancy and whether these accessory molecules could be promising drug targets for combinatorial treatment of various pregnancy disorders." (PMID 32508811, 2020).
prion disease (5 papers, 2012 to 2025). A transmissible disease that is caused by a protein that is able to induce abnormal folding of normal cellular proteins, leading to characteristic spongiform brain changes, which are associated with neuronal loss without an inflammatory response. "TLR2 and TLR4 signaling are important for sensing damage-associated molecular patterns (DAMPs) and has been shown to be implicated in prion disease, as knocking out either of these receptors in mice accelerates disease." (PMID 40532025, 2025). "Subsequently, transgenic mice with defective TLR4 signaling causing them to be hyporesponsive to lipopolysaccharide (LPS) were found to exhibit a significantly accelerated rate of prion disease development in comparison to their wild-type counterparts." (PMID 22363497, 2012). "Previous studies have demonstrated that TLR4 mutant mice exhibit a shorter incubation time than control mice in prion disease." (PMID 38698886, 2024). "In a prion disease model, both pyroptosis and autophagy occurred in PrP106–126-treated microglia via the TLR4-TRIF pathway." (PMID 38007535, 2023). "Furthermore, TLR4 mutant mice exhibited a shorter incubation time than control mice in prion disease." (PMID 38698886, 2024). "Further evidence that TLRs may be important in the regulation of the microglial response in prion diseases stems from the observation that mice with defective TLR4 signaling, making them hyporesponsive to LPS, exhibit an accelerated rate of prion disease." (PMID 22363497, 2012).
prostatic hyperplasia (5 papers, 2016 to 2025). "This study was aimed to evaluate whether single nucleotide polymorphisms (SNPs) of TLR4 and common living habits of prostate hyperplasia (BPH) patients would affect the subjects’ risk and prognosis." (PMID 30944713, 2019). "In conclusion, modulation of TGF-β induced EMT by LPS/TLR4 axis provides a link between prostatic hyperplasia and inflammation." (PMID 27243216, 2016). "Yao found that during prostatic hyperplasia, LPS/Toll-like receptor 4 signaling could upregulate transforming growth factor-β (TGF-β), which plays a role in the pathogenesis of BPH." (PMID 32375790, 2020). "In addition, it has been suggested that LPS/TLR4 (Toll-like receptor 4) signaling enhances the TGF-β response during prostatic hyperplasia." (PMID 30728806, 2019). "In this study, we report that BAMBI acts as a regulator between LPS/TLR4 signalling and TGF-β-induced EMT in vitro during prostatic hyperplasia." (PMID 27243216, 2016). "Here we report that LPS/TLR4 signalling induces down-regulation of the bone morphogenic protein and activin membrane-bound inhibitor (BAMBI), which enhances TGF-β signalling in the EMT process during prostatic hyperplasia." (PMID 27243216, 2016).
Respiratory tract infection (5 papers, 2005 to 2024). An infection of the upper or lower respiratory tract. "Risk factors for respiratory tract infections include increased age and smoking, both of which may affect TLR4 expression." (PMID 16219107, 2005). "contribute largely to respiratory tract infections and play a major role in the initiation and progression of inflammation through activation of innate immune signalling pathways by binding to TLR4-MD-2 receptors." (PMID 38310564, 2024). "Several MyD88 dependent TLRs are known to be important for the innate immune response to respiratory tract infection with K. pneumoniae, particularly TLR4 and TLR9, and during late stage infection or in the presence of high bacterial numbers, TLR2." (PMID 25254554, 2014).
retinal diseases (5 papers, 2012 to 2023). "In addition, other retinal disease-causing genes related to AMD were mainly expressed in clusters P4, P6 and P7, but some susceptibility genes, such as C2, FBLN5, and TLR4, were highly expressed in the macular cluster." (PMID 34977041, 2021). "TLR2 and TLR4 are expressed widely in various retina cells including Müller cells, retina pigment cells, microglia and astrocytes, made them possible critical mediators in the retinal diseases." (PMID 27297042, 2016). "Several endogenous TLR4 activators are upregulated during photoreceptor oxidative injury in vivo, such as HMGB1, suggesting that they may be a source of TLR4 activation during retinal disease." (PMID 22615780, 2012). "Therefore, regulating TLR4 activity, or the expression of endogenous damage response molecules to prevent TLR4 activation, may be a potential therapeutic target for retinal diseases such as AMD." (PMID 22615780, 2012). "Therefore, TLR4 is an important regulator of photoreceptor viability in culture, and may be an important element in the pathogenesis of retinal diseases where inflammation is a factor." (PMID 22615780, 2012).
rheumatic diseases (5 papers, 2008 to 2024). "The data suggest possible involvement of TLR4 in BD, although TLR4 has been also implicated in other rheumatic diseases." (PMID 18234118, 2008). "Taken together, the aim of the present review is to describe how CUR, with its potential anti-inflammatory effects, is able to modulate TLR-4 signaling pathway in neuroinflammatory and rheumatic diseases." (PMID 32225104, 2020). "In addition, the previously reported relationships with TLR4 genetic variants (receptors with LPS as a ligand) may serve to confirm, as suggested by the results of the present metabolomic study, the involvement of the microbiome in the development of rheumatic diseases." (PMID 34299006, 2021). "Despite TLR4 being one of the most important receptors of the innate immunity and having a key role in the development of several rheumatic diseases, there are no studies on the specific effect and signalling of RBP4 on different articular cells like chondrocytes or synoviocytes." (PMID 38275649, 2024).
salmonellosis (5 papers, 2012 to 2021). Infections with bacteria of the genus salmonella. "Previous studies have also shown that TLR4 plays a significant role in the susceptibility of mammals and chickens to systemic salmonellosis." (PMID 27199963, 2016). "TLR4 has been shown to play a significant role in the susceptibility of mammals and chickens to systemic salmonellosis." (PMID 24025421, 2013). "At later time points, substantial neutrophil infiltration was observed even in mice deficient in MyD88 or TLR4 suggesting that multiple partially redundant pathways triggered neutrophil infiltration at high Salmonella loads in agreement with previous data for systemic salmonellosis." (PMID 22586458, 2012). "Genetic resistance of chickens to systemic salmonellosis seems to be associated with genomic regions carrying the candidate genes NRAMP1 (natural resistance-associated macrophage protein, now SLC11A1), MHC, TLR4 and the quantitative trait locus SAL1." (PMID 34563266, 2021). "Not surprisingly, TLR4 plays an important role in invasive Salmonellosis." (PMID 23055923, 2012). "Potential immunomodulating treatment strategies for invasive Salmonellosis could target the pathogen directly (e.g., based on drugs targeting T3SS or flagella) or target key host response proteins (e.g., TLR4, NLRC4, or IL-1β) depending on the phase of the immune response." (PMID 23055923, 2012).
schistosomiasis (5 papers, 2018 to 2023). An infectious disease caused by parasitic trematodes of the genus Schistosoma that colonize human blood vessels and release eggs that can cause granulomatous reactions leading to acute (swimmer's itch or acute schistosomiasis syndrome) or chronic disease. "Among PRRs, Toll-like receptor 4 (TLR4) plays a significant role in schistosomiasis by activating signaling in the immune system and ECs." (PMID 37908354, 2023). "This study demonstrates that TLR4 combined with IFN-γ can activate the MSC group with positive effects on the pathology of schistosomiasis by modulating Th subsets at some degree." (PMID 32503644, 2020). "Both TLR3 and TLR4 can mediate NKs cell activation during schistosomiasis." (PMID 36339337, 2022). "Although the mesenchymal stem cell (MSC) is being used to treat different immune-disturbance complications, current investigation revealed that TLR4 combined with IFN-γ can activate the MSC group with positive effects on the pathology of schistosomiasis by modulating Th subsets at some degree." (PMID 36339337, 2022). "So, we questioned whether TLR2/TLR4-ligated MSC could also modulate Th1/Th2 responses and thus have different roles in the schistosomiasis model." (PMID 32503644, 2020). "In conclusion, our experiment demonstrates that only the TLR4+IFN-γ-activated MSC group did show positive effects on the pathology of schistosomiasis by enhancing Th1-polarized response, which improves our knowledge about the MSC-based cell therapy for the treatment of schistosomiasis." (PMID 32503644, 2020). "In human schistosomiasis, S. mansoni glycolipid induces DC-driven Th1 immune responses by the cooperation of DC-specific intercellular adhesion molecule-3-grabbing nonintegrin (DC-SIGN) and TLR4." (PMID 36339337, 2022).
staphylococcus aureus infection (5 papers, 2016 to 2024). An infectious process in which the bacteria Staphylococcus aureus is present. "Other reports indicated that Staphylococcus aureus infections activate TLR4, which worsens AD." (PMID 37179569, 2023).